IGSF6 (immunoglobulin superfamily member 6)
Synonyms: DORA
Tractability: Antibody: its Gene Ontology location is reachable by antibodies, with high confidence; UniProt predicts a signal peptide or a membrane-spanning region.
Gene: Protein-coding gene on chromosome 16 (21,639,550 to 21,652,611, reverse strand). Ensembl gene ENSG00000140749.
Subcellular location: Membrane
Gene Ontology:
Molecular function: transmembrane signaling receptor activity
Biological process: cell surface receptor signaling pathway; immune response
Cellular component: plasma membrane; membrane
Genetic constraint (gnomAD): Loss-of-function variants: 15 observed, 12.62 expected, observed/expected ratio (o/e) 1.19, 90% interval 0.79 to 1.76. The upper end of that interval is the gene's LOEUF score, 1.76, which puts it in group 6 of 6, group 1 being the genes least tolerant of losing a copy. Missense variants: 177 observed, 190.68 expected, observed/expected ratio (o/e) 0.93, 90% interval 0.82 to 1.05. Synonymous variants: 68 observed, 77.26 expected, observed/expected ratio (o/e) 0.88, 90% interval 0.72 to 1.08.
Homologues: Orthologues: chimpanzee IGSF6 (99% identical), macaque IGSF6 (94% identical), rabbit IGSF6 (71% identical), pig IGSF6 (68% identical), guinea pig IGSF6 (68% identical), rat Igsf6 (66% identical), mouse Igsf6 (62% identical), dog IGSF6 (61% identical), zebrafish si:ch211-139g16.8 (21% identical).
Diseases named in the same sentence as IGSF6 in open-access papers:
IGSF6 is named in the same sentence as 19 diseases in open-access papers, as found by Europe PMC text mining. Sharing a sentence is not in itself a finding about the gene and the disease. The quoted sentences say what the papers report.
inflammatory bowel disease (7 papers, 2020 to 2024). A spectrum of small and large bowel inflammatory diseases of unknown etiology. "Immunoglobulin superfamily member 6 (IGSF6) has been reported to be associated with inflammatory bowel disease." (PMID 36602538, 2023). "IGSF6 was considered to be closely related to the susceptibility of inflammatory bowel disease." (PMID 33169786, 2020). "Some studies reported the involvement of IGSF6 in the immunoregulation of atherosclerosis and inflammatory bowel disease." (PMID 39108261, 2024). "The protein-coding gene IGSF6, belonging to the immunoglobulin superfamily member 6, is involved in the regulation of inflammatory bowel disease." (PMID 37671094, 2023). "IGSF6 was reported to be involved in the immune regulations of atherosclerosis and inflammatory bowel disease." (PMID 36387234, 2022).
cervical cancer (1 paper, 2022). A primary or metastatic malignant neoplasm involving the cervix. "As the expressions of IGSF6, TLR10, FCRL3, and IFI30 were all upregulated in cervical cancer and the higher expressions of IGSF6, FCRL3, and IFI30 predicted better prognosis, we asked if the combination of these four genes was associated with the risks of cervical cancer." (PMID 36387234, 2022). "To validate the expressions of IGSF6, TLR10, FCRL3, and IFI30 in cervical cancer, we performed immunohistochemistry against these genes, respectively." (PMID 36387234, 2022). "Apart from this, an intriguing notion is that the four genes (IGSF6, TLR10, FCRL3, and IFI30) were also upregulated in cervical cancer compared to normal tissues, while their high expressions predicted better prognosis." (PMID 36387234, 2022). "In line with the results from the transcriptomics, we identified stronger expressions of IGSF6, TLR10, FCRL3, and IFI30 in cervical cancer tissues compared to normal tissues." (PMID 36387234, 2022). "Consistently, the expressions of IGSF6, TLR10, FCRL3, and IFI30 were upregulated in cervical cancer in the validation cohort." (PMID 36387234, 2022). "By univariant Cox and LASSO analyses, we finally got 4 genes (IGSF6, TLR10, FCRL3, and IFI30) that were closely correlated with both the CD8+ T cell infiltration and the prognosis of cervical cancer." (PMID 36387234, 2022). "To validate the immune infiltration pattern, the expressions of IGSF6, TLR10, FCRL3, and IFI30, and the correlation between them, we downloaded the GSE151666 dataset from the GEO database as a validation cohort, which included 68 cervical cancer patients." (PMID 36387234, 2022). "Based on these facts, we thought that the discovery of the 4 novel genes (IGSF6, TLR10, FCRL3, and IFI30) in cervical cancer might shed light on the clinical treatments of cervical cancer as well." (PMID 36387234, 2022).
colorectal cancer (1 paper, 2023). A primary or metastatic malignant neoplasm that affects the colon or rectum. "Strikingly, our experimental data indicate that IGSF6 exhibits the strongest expression in human lymphocytes while varies expression in the THP-1 and colorectal cancer cell lines, underscoring its potential significance in these cellular environments." (PMID 37989761, 2023).
COVID-19 (1 paper, 2021). A disease caused by infection with severe acute respiratory syndrome coronavirus 2. "One example of a changed APA event in COVID-19 compared with non-COVID-19 is given for the IGSF6 gene (Immunoglobulin Superfamily Member 6), with a shorter 3′UTR predominating in COVID-19 samples compared with matched non-COVID-19 samples in GEO." (PMID 34777369, 2021).
esophageal carcinoma (1 paper, 2023). A primary or metastatic malignant neoplasm involving the esophagus. "It was suggested that IGSF6 expression was increased in cancers such as bladder urothelial carcinoma (BLCA), esophageal carcinoma (ESCA), and glioblastoma multiforme (GBM), and was decreased in some others, particularly LUAD." (PMID 38037023, 2023).
lung adenocarcinoma (1 paper, 2023). A carcinoma that arises from the lung and is characterized by the presence of malignant glandular epithelial cells. "However, the specific role of IGSF6 in the anti-tumor immunity within lung adenocarcinoma (LUAD) remains unclear." (PMID 38037023, 2023).
neuroblastoma (1 paper, 2025). Neuroblastoma (NB) is the most common solid, extracranial childhood tumor. "High expression levels of CCL2, CCL4, CCL21, CD200, CXCR3, and IGSF6 were significantly associated with improved survival in neuroblastoma patients (all p < 0.001)." (PMID 40718780, 2025). "Our study demonstrates that tertiary lymphoid structure (TLS)-related genes play a crucial role in neuroblastoma (NB) prognosis, with a 6-gene TLS signature (CCL2, CCL4, CCL21, CD200, CXCR3, and IGSF6) serving as a promising prognostic biomarker for NB." (PMID 40718780, 2025).
rectal tumor (1 paper, 2023). "Interestingly, IGSF6 was significative up-regulated in both colon and rectal tumor versus normal tissue." (PMID 37989761, 2023). "Furthermore, we constructed a tissue microarray on colon or rectal tumor tissues containing a large cohort of CRC patients (n = 302) and detected the expression of IGSF6, CD4+ and CD8+ T cell with multiple immunofluorescences." (PMID 37989761, 2023).
Sepsis (1 paper, 2024). Sepsis is defined as life-threatening organ dysfunction caused by a dysregulated host response to infection. "Key diagnostic biomarkers, including PIM1, HIST1H1C, and IGSF6, have been identified and incorporated into an accurate riskScore model for the prognosis of sepsis." (PMID 39108261, 2024).
uveitis (1 paper, 2025). An inflammatory process affecting a part of or the entire uvea. "To identify core regulatory genes shared between AS and uveitis, we first intersected genes from WGCNA-derived disease-associated modules and cross-disease DEGs, yielding five candidate genes: SORL1, TLR8, HLX, SLC25A20, and IGSF6." (PMID 40929101, 2025).
cancer (4 papers, 2022 to 2024). A tumor composed of atypical neoplastic, often pleomorphic cells that invade other tissues. "Lastly, IGSF6 is a novel member of the immunoglobulin superfamily with anti-tumour activity on macrophages and immune cell infiltration in cancer and inflammation tissue." (PMID 38571307, 2024). "The results showed that the expression of IGSF6 was positive correlated with tumor-infiltrating lymphocytes in various cancers, especially for CRC." (PMID 37989761, 2023). "RNA-seq data from TCGA were used to analyze the IGSF6 expression across 33 types of cancers." (PMID 38037023, 2023). "Moreover, we found that IGSF6 manifests a favorable expression trajectory in the MMR-proficient as compared to MMR-deficient in CRC, which suggested the potential role of IGSF6 as a potential biomarker of cancer therapy in MMR-proficient CRC." (PMID 37989761, 2023). "The expression levels of IGSF6, CD8+ T cells, CD4+ T cells and CD68+ macrophage cells in cancer tissues from CRC patients and CRC cell lines were evaluated." (PMID 37989761, 2023).
tumor (4 papers, 2023 to 2024). "To evaluate IGSF6 can be used as a biomarker for immune infiltration, we assessed the association between IGSF6 expression and tumor-infiltrating lymphocytes in TCGA datasets." (PMID 37989761, 2023). "IGSF6 expression was associated with the infiltration of CD8+ T cells and CD4+ T cells in tumors, indicating an active immune response within the tumor microenvironment." (PMID 39108261, 2024). "Unexpectedly, IGSF6 levels are highly expressed in tumor tissues as compared with adjacent normal tissues (p < 0.0001)." (PMID 37989761, 2023). "The results showed a consistent trend, where the expression of IGSF6 decreased with tumor progression." (PMID 38037023, 2023). "LUAD cells and M1 macrophages with IGSF6 knockdown were subcutaneously injected into the mice, and tumor progression was monitored over time." (PMID 38037023, 2023). "IGSF6 expression showed a positive correlation with immune infiltrates exhibiting anti-tumor activity, particularly M1 macrophages." (PMID 38037023, 2023). "As expected, IGSF6 levels are more highly expressed in tumor tissues from chemosensitive patients than from chemoresistance patients." (PMID 37989761, 2023). "To investigate the impact of IGSF6 on M1 polarization and anti-tumor activity, we transfected M0 macrophages with specific siRNAs targeting IGSF6 and then observed the changes in M1 polarization and activity." (PMID 38037023, 2023). "Compared to the control group, the si-IGSF6 group exhibited accelerated tumor progression (p = 0.0017)." (PMID 38037023, 2023). "To investigate the potential role of IGSF6 in the anti-tumor immune response within LUAD, we performed enrichment analysis on the top 300 genes associated with IGSF6 in LUAD." (PMID 38037023, 2023). "To further investigate the impact of IGSF6 on the anti-tumor activity of M1 macrophages in vivo, we conducted experiments using nude mice." (PMID 38037023, 2023). "Lastly, we discovered the crucial role of IGSF6 in the anti-tumor activity of M1 macrophages in LUAD." (PMID 38037023, 2023). "The results showed that the si-IGSF6 group had enhanced tumor progression compared to the control group (p = 0.0229)." (PMID 38037023, 2023). "To further investigate the impact of IGSF6 on the anti-tumor activity of M1 macrophages, we used siRNA to knock down IGSF6 expression in M1 and then observed the change in cell biology." (PMID 38037023, 2023). "By further comparing the expression of IGSF6 in paired tumor tissues and adjacent non-tumor tissues (n = 55), we found a significant downregulation of IGSF6 expression in tumor tissues (p < 0.001)." (PMID 38037023, 2023). "Importantly, the knockdown of IGSF6 resulted in a reduction in the anti-tumor activity of M1 macrophages, thereby promoting tumor progression." (PMID 38037023, 2023). "IGSF6 was more highly expressed in CRC tumor tissues than adjacent normal tissues." (PMID 37989761, 2023). "Furthermore, we investigated the relationship between IGSF6 expression and immune cell components in tumor microenvironment." (PMID 37989761, 2023). "IGSF6 is a molecule that is essential for the anti-tumor activity of macrophages in LUAD." (PMID 38037023, 2023). "Interestingly, multiple immunofluorescences analysis indicated a strong positive correlation between IGSF6 expression and tumor-infiltrating lymphocytes, including CD4+ and CD8+ T cell, in CRC tumors." (PMID 37989761, 2023). "IGSF6 expression was upregulated in CRC tissues and high expression of IGSF6 correlated with an active immune microenvironment and a favorable prognosis and furthermore it may facilitate immune mediated tumor killing." (PMID 37989761, 2023). "Furthermore, we have found that IGSF6 plays a critical role in the anti-tumor activity of M1 macrophages in LUAD." (PMID 38037023, 2023). "Based on these findings, we hypothesized that IGSF6 might affect the T cell-induced anti-tumor response by enhancing the activation and antigen processing of DCs and M1 in LUAD." (PMID 38037023, 2023).
tumor (continued). "Moreover, we demonstrated overexpression of IGSF6 was associated with a high density of CD8+ T cell and CD4+ T cell tumor-infiltrating lymphocytes." (PMID 37989761, 2023). "Moreover, expression of IGSF6 correlated with tumor-infiltrating lymphocytes were confirmed in GSE39582 dataset, which supported that IGSF6 could be a potential biomarker to improve clinical applications of current immunotherapies." (PMID 37989761, 2023). "The proportion of tumor-infiltrating immune cells in LUAD was assessed using FCM, and their correlation with IGSF6 expression in tumor tissues was analyzed." (PMID 38037023, 2023). "We next detected IGSF6 expression, CD4+ T cell, CD8+ T cell and CD68+ macrophage cell from pathological tumor specimens with IHC." (PMID 37989761, 2023). "To determine the regulatory role of IGSF6 on macrophage activity in LUAD, we employed ELISA, FCM, and tumor-bearing models." (PMID 38037023, 2023). "It was found that compared to that in adjacent non-tumor tissues, IGSF6 expression was significantly decreased in LUAD tumor tissues (p < 0.001)." (PMID 38037023, 2023). "Furthermore, only IGSF6, among IGSF family genes, showed a strong positive correlation with tumor-infiltrating lymphocytes in CRC patients, including MMR-deficient and MMR-proficient tumors." (PMID 37989761, 2023). "To validate the results obtained from the bioinformatics analysis, we conducted a study in which we measured the expression of IGSF6 in tumor tissues (n = 93) and adjacent non-tumor tissues (n = 93) collected from LUAD patients." (PMID 38037023, 2023). "Additionally, the knockdown of IGSF6 in M1 macrophages decreased the production of IL-12 and TNFα by M1 macrophages and accelerated the LUAD progression, indicating that IGSF6 is involved in the anti-tumor activity of M1 macrophages." (PMID 38037023, 2023). "There were more tumor-infiltrating immune cells in tumor tissues of the IGSF6high group than in those of the IGSF6low group, indicating that MMR-proficient CRC tissues with high levels of IGSF6 had a tumor microenvironment with an activated adaptive immune phenotype." (PMID 37989761, 2023). "In addition, we confirmed the decreased IGSF6 protein levels in tumor tissues compared to those in paired non-tumor tissues using western blotting." (PMID 38037023, 2023). "Additionally, to confirm the role of IGSF6 in antigen processing by M1 macrophages in vivo, we injected CD4+ T cells, LUAD cells, and M1 macrophages with IGSF6 knockdown into nude mice and monitored tumor progression." (PMID 38037023, 2023). "Interestingly, a strong positive correlation between IGSF6 expression and tumor-infiltrating lymphocytes can be found in MMR-proficient tumors, indicating that IGSF6 could be an immunotherapy biomarker for MMR-proficient CRC patients." (PMID 37989761, 2023).
bacterial infection (1 paper, 2024). "IGSF6 expression is sustained by microbiota and significantly upregulated upon bacterial infection." (PMID 39108261, 2024).
IGSF6 also shares sentences with these, for which no sentence is quoted: atherosclerosis (3 papers); Alzheimer disease (1); Crohn disease (1); glioblastoma multiforme (1); glioma (1); Salmonella Infections (1).